TAT (tyrosine aminotransferase)
Description:
Transaminase involved in tyrosine breakdown. Converts tyrosine to p-hydroxyphenylpyruvate. Can catalyze the reverse reaction, using glutamic acid, with 2-oxoglutarate as cosubstrate (in vitro). Has much lower affinity and transaminase activity towards phenylalanine.
Tractability: Small molecule: it has a high-quality binding pocket. PROTAC: its protein half-life has been measured.
Target class: Enzyme; Transferase
Gene: Protein-coding gene on chromosome 16 (71,565,660 to 71,577,095, reverse strand). Ensembl gene ENSG00000198650.
Pathways (Reactome):
Metabolism: Tyrosine catabolism
Gene Ontology:
Molecular function: identical protein binding; L-tyrosine-2-oxoglutarate transaminase activity; protein binding; amino acid binding; catalytic activity; pyridoxal phosphate binding; transaminase activity
Biological process: 2-oxoglutarate metabolic process; glutamate metabolic process; L-tyrosine catabolic process; L-phenylalanine catabolic process; amino acid metabolic process; aromatic amino acid family catabolic process; aromatic amino acid metabolic process; cellular response to insulin stimulus; cellular response to retinoic acid; liver regeneration; response to cAMP; response to cortisol; response to dexamethasone; response to ethanol; response to glucocorticoid; response to mercury ion; response to oxidative stress
Cellular component: cytosol
Genetic constraint (gnomAD): Loss-of-function variants: 35 observed, 55.01 expected, observed/expected ratio (o/e) 0.64, 90% interval 0.49 to 0.84. The upper end of that interval is the gene's LOEUF score, 0.84, which puts it in group 3 of 6, group 1 being the genes least tolerant of losing a copy. Missense variants: 525 observed, 594.92 expected, observed/expected ratio (o/e) 0.88, 90% interval 0.82 to 0.95. Synonymous variants: 197 observed, 216.1 expected, observed/expected ratio (o/e) 0.91, 90% interval 0.81 to 1.03.
Gene-disease validity (ClinGen):
ClinGen rates the evidence that TAT causes each of these diseases.
tyrosinemia type II (autosomal recessive): Definitive. Tyrosinemia type 2 is an inborn error of tyrosine metabolism characterized by hypertyrosinemia with oculocutaneous manifestations and, in some cases, intellectual deficit.
Homologues: Orthologues: chimpanzee TAT (99% identical), macaque TAT (97% identical), dog TAT (93% identical), mouse Tat (92% identical), rabbit TAT (92% identical), rat Tat (92% identical), pig TAT (90% identical), guinea pig TAT (87% identical), tropical clawed frog tat (74% identical), zebrafish tat (70% identical), Drosophila melanogaster Tat (48% identical), Caenorhabditis elegans tatn-1 (42% identical). Paralogues in human: GPT (23% identical), GPT2 (22% identical), ACCSL (18% identical), AADAT (17% identical), KYAT1 (17% identical), ACCS (17% identical), KYAT3 (16% identical).